PARD3 (par-3 family cell polarity regulator)
Diseases named in the same sentence as PARD3 in open-access papers (continued):
Sharing a sentence is not in itself a finding about the gene and the disease.
PARD3 also shares sentences with these, for which no sentence is quoted: diabetes (4 papers); Insulin resistance (2); lung adenocarcinoma (2); acute myeloid leukemia (1); adrenal hypoplasia (1); anaplastic thyroid cancer (1); asthma (1); bladder urothelial carcinoma (1); cardiovascular disease (1); cholangiocarcinoma (1); cleft lip (1); colon adenocarcinoma (1); craniorachischisis (1); cyclopia (1); diffuse large B-cell lymphoma (1); head and neck cancer (1); infection (1); inflammatory bowel disease (1); Kidney Cyst (1); low grade glioma (1); lung carcinoma (1); mental disorder (1); neural tube defect (1); neurological diseases (1); osteosarcoma (1); ovarian serous cystadenocarcinoma (1); pancreatic adenocarcinoma (1); pancreatic cancers (1); Parkinson’s (1); periodontitis (1).
A further 14 diseases each share a sentence with PARD3 in 1 paper.